RBP4 (retinol binding protein 4)
Diseases named in the same sentence as RBP4 in open-access papers (continued):
Sharing a sentence is not in itself a finding about the gene and the disease.
craniosynostosis (2 papers, 2007 to 2015). Craniosynostosis is defined as the premature fusion of one or more cranial sutures leading to secondary distortion of skull shape resulting in skull deformities with a variable presentation. "Taken together with our data on RBP4 expression during suture fusion and epidemiological evidence linking excess RA with craniosynostosis and other developmental anomalies we speculate that perturbations in the RBP4-retinol-RA axis may contribute to the occurrence of craniosynostosis." (PMID 18076769, 2007). "Our finding of RBP4 in osteocytes on the ectocranial surface of bone directly overlying the suture mesenchyme and by cells lining the osteogenic fronts, and its dramatic downregulation in suture fusion now implicates a role for it in suture morphogenesis and craniosynostosis." (PMID 18076769, 2007).
diabetic cardiomyopathy (2 papers, 2022 to 2024). Diabetic cardiomyopathy is a disorder of the heart muscle in people with diabetes. "Thiscase-control study aims to determine the association between serum RBP4 levelsand diabetic cardiomyopathy (DCM)." (PMID 39076230, 2022).
diabetic neuropathy (2 papers, 2022 to 2024). A chronic, pathological complication associated with diabetes mellitus, where nerve damages are incurred due to diabetic microvascular injury involving small blood vessels that supply these nerves, resulting in peripheral and/or autonomic nerve dysfunction. "IV: Intravenous; N: Number of participants; CT: Clinical trial; TTR: Transthyretin; SC: Subcutaneously; RBP4: Retinol-binding protein 4; QoL: Quality of life; QoL-DN: Quality of life-diabetic neuropathy; MAE: Major adverse event; GN: Glomerulonephritis; TCP: Thrombocytopenia." (PMID 39044869, 2024).
esophageal squamous cell carcinoma (2 papers, 2012 to 2022). Esophageal squamous cell carcinoma (ESCC) is a type of esophageal carcinoma (EC) that can affect any part of the esophagus, but is usually located in the upper or middle third. "Similarly, methylation of RBP4 in esophageal squamous cell carcinoma seems more frequent than that in adjacent esophagus tissues, however, the difference was not statistically significant (P=0.08)." (PMID 36632438, 2022). "For example, RBP4 methylation was investigated in esophageal squamous cell carcinoma." (PMID 22363757, 2012).
glioblastoma (2 papers, 2022 to 2025). The most malignant astrocytic tumor (WHO grade IV). "However, the expression and function of RBP4 in glioblastoma (GBM) are completely unknown." (PMID 36632438, 2022).
hepatic (2 papers, 2011 to 2024). "We attempted to reduce selection bias by excluding major causes (chronic hepatic and renal disease) likely to influence RBP4 levels and birthweight, but the bias may still be present." (PMID 39710423, 2024). "However, thus far, the relationship between hepatitis E and RBP4 remains unknown, and the relationship between HEV and RBP4 and the effect of this interaction on disease severity is unclear." (PMID 22308156, 2011).
hyperandrogenism (2 papers, 2018 to 2025). Excessive secretion of androgens from the adrenal glands or gonads. "The present study demonstrated that the adipokine profile in adolescent girls with menstrual disorders and hyperandrogenism differs from that observed in girls with regular menstrual cycles, particularly in terms of adiponectin, RBP-4 and vaspin concentrations." (PMID 41303021, 2025).
influenza (2 papers, 2015 to 2025). An acute viral infection of the respiratory tract, occurring in isolated cases, in epidemics, or in pandemics; it is caused by serologically different strains of viruses (influenzaviruses) designated A, B, and C, has a 3-day incubation period, and usually lasts for 3 to 10 days. "The results showed that RBP4 expression was significantly higher in the blood of IAV-patients than in healthy individuals, which is consistent with previous findings in nasopharyngeal aspirate samples from influenza patients." (PMID 41144502, 2025).
lipodystrophy (2 papers, 2017 to 2020). A congenital or acquired disorder characterized by abnormal loss or redistribution of the adipose tissue in the body. "This group includes mice with adipose-specific deficiency of the insulin receptor, or of Raptor/mTORC1, both of which develop lipodystrophy, and mice with adipose-specific overexpression of RBP-4 which show adipose tissue inflammation with macrophage infiltration." (PMID 29232702, 2017).
lung disease (2 papers, 2017 to 2024). "In ICU patients with underlying pulmonary disease, lower RBP4 levels were noted in septic patients than in non-septic patients." (PMID 28588245, 2017).
malaria (2 papers, 2017 to 2024). Malaria is a serious and sometimes fatal disease caused by a parasite that commonly infects a certain type of mosquito which feeds on humans. "RBP4 mean concentration levels were high in healthy children 0.83 μmol/L (SD 0.08), compared to in children that were sick with malaria 0.82 μmol/L (SD 0.14), having a mean difference of 0.01 μmol/L." (PMID 39728830, 2024). "However, the mean concentration levels of RBP4 and Tg were high in healthy children (RBP4 M = 0.83 μmol/L, Tg M =20.91 μg/L) compared to those that were infected with malaria (RBP4 M = 0.82 μmol/L, Tg M = 19.98 μg/L), but their difference was not statistically significant." (PMID 39728830, 2024).
malnutrition (2 papers, 2025). Inadequate nutrition resulting from poor diet, malabsorption, or abnormal nutrient distribution. "First, malnutrition, as indicated by low serum albumin, is associated with reduced hepatic protein synthesis and has been linked to lower RBP4 levels." (PMID 40881125, 2025). "RBP4 is also recognized as a marker of adequate nutrition, with low serum concentrations indicating malnutrition at various stages." (PMID 40217967, 2025).
Matthew-Wood syndrome (2 papers, 2021 to 2025). Matthew-Wood syndrome is a rare clinical entity including as main characteristics anophthalmia or severe microphthalmia, and pulmonary hypoplasia or aplasia. "Given the adverse contribution of RBP4 to the response of ischemic injury in mice and the phenotype observed in patients with Matthew-Wood syndrome, RBP4 rather than STRA6 might be a potential therapeutic approach for the treatment of MI." (PMID 41035698, 2025).
migraine (2 papers, 2024 to 2025). "The results showed that the serum level of RBP4 was significantly lower in migraine patients and the hs-CRP level was also significantly higher in these patients than in controls." (PMID 39539367, 2024).
mood disorder (2 papers, 2015 to 2022). A cognitive disorder a disturbance in which the person's mood is hypothesized to be the main underlying feature. "Taken together, RBP-4/TTR complex, thyroxine and vitamin A are all present in the CSF and participate in brain maturation and, cognitive, acquisition of memory and behavioral activities and may be implicated in mood disorders." (PMID 26645624, 2015).
morbid obesity (2 papers, 2013 to 2022). An excess of body weight, normally defined as an individual with a body mass index greater than 35 or a body weight greater than one hundred percent of ideal body weight. "Bariatric surgeries are regarded as a safe and effective way of treating morbid obesity and are associated with alterations in molecules such as Vitamin D and retinol-binding protein 4 (RBP4)." (PMID 36686076, 2022). "To summarise, circulating RBP4 may play a major role in lipid metabolism in morbid obesity in which it is associated with an increase in triglyceride levels and contributes to the formation of small HDL, independently of insulin-resistant state." (PMID 24223837, 2013). "Our study reveals that systemic RBP4 levels could play an important role in lipid metabolism in morbid obesity, increasing triglyceride levels and contributing to the formation of small HDL." (PMID 24223837, 2013).
muscle atrophy (2 papers, 2024 to 2025). The loss of muscle tissue due to inactivity or disease. "Therefore, the aim of the present study was to investigate the effects of RBP4 on muscle fat infiltration and muscle atrophy as well as the underlying mechanisms in a mouse model of denervation‐induced muscle atrophy." (PMID 39031684, 2024). "Our results suggest that lowering RBP4 levels might serve as a promising therapeutic approach for prevention and treatment of muscle atrophy." (PMID 39031684, 2024).
non-alcoholic steatohepatitis (2 papers, 2014 to 2017). "This meta-analysis is to determine whether NAFLD, non-alcoholic steatohepatitis (NASH) and simple steatosis (SS) patients have altered RBP4 levels." (PMID 28931435, 2017).
oral squamous cell carcinoma (2 papers, 2016 to 2019). "On the contrary, RBP4 was recently reported as a potential biomarker of oral squamous cell carcinoma, in combination with clusterin, haptoglobin, complement C3c, and proapolipoprotein A1." (PMID 30813269, 2019).
rheumatoid arthritis (2 papers, 2014 to 2024). A chronic, systemic autoimmune disorder characterized by inflammation in the synovial membranes and articular surfaces. "Several adipokines other than RBP4 and including adiponectin, leptin and resistin can participate importantly in the pathophysiology of rheumatoid arthritis (RA), a prototypic inflammatory disease." (PMID 24651174, 2014). "Moreover, altered levels of RBP4 have been reported in patients with rheumatic diseases, including rheumatoid arthritis (RA) and ankylosing spondylitis." (PMID 38275649, 2024). "Whether RBP4 contributes to cardiovascular risk in rheumatoid arthritis (RA) is unknown." (PMID 24651174, 2014).
thyroid cancer (2 papers, 2019). "As an example, in this study, we showed that retinol-binding protein 4 (RBP4) was exclusively found in the urine of patients with HNSCC but not thyroid cancer, indicating that this protein could be a specific HNSCC biomarker." (PMID 30813269, 2019).
vitamin D deficiency (2 papers, 2015 to 2024). A nutritional condition produced by a deficiency of VITAMIN D in the diet, insufficient production of vitamin D in the skin, inadequate absorption of vitamin D from the diet, or abnormal conversion of vitamin D to its bioactive metabolites. "Whether the lower RBP-4 levels in the 25(OH)D-deficient group of IBD patients directly reflect vitamin D deficiency remains uncertain." (PMID 38961351, 2024).
advanced heart failure (1 paper, 2022). Patients with advanced heart failure have severe limitations, experiences symptoms even while at rest and are mostly bedbound patients. "The blood RBP4 levels in patients with advanced heart failure can be improved by implantation of a ventricular assist device." (PMID 35309061, 2022). "The elevation of RBP4 in patients with advanced heart failure may result from upregulation of RBP4 mRNA expression by IL-8." (PMID 35309061, 2022).
amyloid cardiomyopathy (1 paper, 2026). "Current and emerging therapies for TTR amyloid cardiomyopathy (ATTR-CM), including RNAi therapies and potentially CRISPR-based therapies, reduce hepatic transthyretin production and hence decrease serum RBP4, which decreases circulating vitamin A levels." (PMID 42188091, 2026).
angina pectoris (1 paper, 2021). The symptom of paroxysmal pain consequent to MYOCARDIAL ISCHEMIA usually of distinctive character, location and radiation. "Also in subgroup analysis of this study, the RBP4 levels were higher in ACS patients than in patients with stable angina pectoris and the SYNTAX score showed a positive significant correlation with RBP4 in both groups." (PMID 34616228, 2021). "In a study involving both genders RBP4 levels were higher in patients with both ACS and stable angina pectoris compared to patients whose CAD was ruled out by coronary angiography." (PMID 34616228, 2021).
aorticatherosclerosis (1 paper, 2023). "The study showed the expression of RBP4 increased in aorticatherosclerosis in both humans and mice and RBP4 tended to localize in regionsrich in macrophage foam cells." (PMID 39077416, 2023).
arterial disease (1 paper, 2022). "In our previous clinical trials, after 12 weeks of vitamin D therapy, the incidence rate of lower extremity arterial disease in the T2DM group and the level of RBP4 both decreased significantly." (PMID 35082965, 2022).
arteriosclerosis (1 paper, 2022). A vascular disorder characterized by thickening and hardening of the walls of the arteries. "Elevated circulating RBP4 levels have been observed in subjects with previous clinical arteriosclerosis, subclinical arteriosclerosis, and CAD." (PMID 35369314, 2022).
babesiosis (1 paper, 2023). Babesiosis refers to a condition caused by microscopic parasites that infect the red blood cells. "Other identified proteins that differentiated uncomplicated from complicated babesiosis were various complement cascade components (CFI, CFP, C2, SERPING1, C8G), extracellular matrix components (TGFBI), acute phase proteins (ORM1, ITIH2, ITIH4, FGA, TF, RBP4) and lipoproteins (apoE)." (PMID 37353646, 2023).
bone tumors (1 paper, 2013). "Since there is a possibility that one week culturing may affect gene expression of PC3-GFP, expression levels of GFP, RBP4 and PLAC8 in bone tumors were examined by immunohistochemical staining." (PMID 23708710, 2013). "Immunohistochemical staining of GFP, RBP4 and PLAC8 showed that bone tumors formed by injection of the mixture of PC3-GFP/PC3-mock or PC3-GFP/PC3-OPG, contained GFP-positive cells and the expression levels of both RBP4 and PLAC8 were increased in tumor cells from PC3-GFP/PC3-OPG-injected mice." (PMID 23708710, 2013).
cholelithiasis (1 paper, 2022). The presence of crystallized deposits forming in the gallbladder or biliary tree, primarily composed of cholesterol, bilirubin, and bile. "Higher levels of chemerin, retinol-binding protein 4 (RBP-4), and fibroblast growth factor 21 (FGF-21) have been observed in children with cholelithiasis." (PMID 36362164, 2022).
chronic hepatitis B infection (1 paper, 2022). "Some studies have shown that the serum RBP4 expression level of patients with chronic hepatitis B infection is lower than that of healthy people, and it is negatively correlated with the severity of the disease." (PMID 34889069, 2022).
chronic obstructive pulmonary disease (1 paper, 2013). A chronic and progressive lung disorder characterized by the loss of elasticity of the bronchial tree and the air sacs, destruction of the air sacs wall, thickening of the bronchial wall, and mucous accumulation in the bronchial tree. "RBP4 was positively correlated with creatinine and body mass index, and negatively correlated with C-reactive protein and Global Initiative for Chronic Obstructive Lung Disease stage." (PMID 24099047, 2013).
colorectal adenoma (1 paper, 2022). An adenoma that arises from the colon or rectum. "Interestingly, a higher RBP4 level in stool was also identified as a biomarker for noninvasive detection of colorectal adenomas with a high risk of progression." (PMID 36632438, 2022).
colorectal tumors (1 paper, 2025). "Interestingly, our immunohistochemical findings contrast with TCGA transcriptomic data, which did not demonstrate significant differences in RBP4 mRNA levels between colorectal tumors and adjacent tissues." (PMID 41007818, 2025).
coronary stenosis (1 paper, 2014). Narrowing of the coronary artery lumen diameter. "In conclusion, the present study documented RBP4 being a strong predictor of CAD, defined as angiographically significant coronary stenosis." (PMID 25142320, 2014).
crystalline arthritis (1 paper, 2024). "In this study, we aimed to determine the presence of RBP4 in synovial fluid from crystalline arthritis (CA) patients as well as its potential as an articular pro-inflammatory and pro-catabolic factor." (PMID 38275649, 2024).
ductal carcinoma (1 paper, 2008). "There is no report on RBP4 in the literature in connection with ductal vs. lobular breast cancer distinction while ALDH1A1 protein levels were shown to exhibit differences among the ductal carcinoma patients." (PMID 19116033, 2008).
geographic atrophy (1 paper, 2023). "A recent study also compared the plasma RBP4 levels in healthy controls in various age groups and patients with geographic atrophy." (PMID 37510153, 2023). "Moreover, in patients who achieved RBP4 levels below 1 μM (approximately 20 μg/mL) after fenretinide treatment, a lower serum RBP4 level was correlated with a slower rate of geographic atrophy progression." (PMID 37510153, 2023).
glioma (1 paper, 2022). A benign or malignant brain and spinal cord tumor that arises from glial cells (astrocytes, oligodendrocytes, ependymal cells). "Interestingly, gliomas with larger tumor sizes were more prevalent to exhibit positive RBP4 expression compared with the smaller ones (P < 0.001), indicating that RBP4 may participate in GBM progression." (PMID 36632438, 2022).
gout (1 paper, 2024). A condition characterized by painful swelling of the joints, which is caused by deposition of urate crystals. "RBP4 concentration in the synovial fluid of these patients was between 2.44 and 22.62 μg/mL, with a mean concentration of 11.74 ± 5.85 μg/mL (11.53 ± 2.17 μg/mL in gout patients and 11.94 ± 1.30 μg/mL in CPPD patients)." (PMID 38275649, 2024). "In line with this, RBP4 levels were also not significantly different between pseudogout and gout patients." (PMID 38275649, 2024).
Granuloma (1 paper, 2026). A compact, organized collection of mature mononuclear phagocytes, which may be but is not necessarily accompanied by accessory features such as necrosis. "Therefore, during MTB infection, decreased expression of RBP4 may hinder the formation of foam macrophages and slow the development of granulomas and caseous necrosis in TB." (PMID 41477556, 2026).
Hypercalcemia (1 paper, 2015). An abnormally increased calcium concentration in the blood. "RBP4 levels are significantly and independently associated with hypercalcemia in patients on dialysis." (PMID 25119682, 2015). "Given the important associations with RBP4 and hypercalcemia, it would have been useful to measure apo-RBP4 and free ROH." (PMID 25119682, 2015). "High levels of RBP4 were significantly and independently associated with hypercalcemia in dialysis patients." (PMID 25119682, 2015).
hyperthyroidism (1 paper, 2021). Overactivity of the thyroid gland resulting in overproduction of thyroid hormone and increased metabolic rate. "The RBP4/PiC/SIRT3 pathway is thus involved in the opening of the renal mPTP in offspring rats with hyperthyroidism." (PMID 33503180, 2021).
inflammatory bowel disease (1 paper, 2021). A spectrum of small and large bowel inflammatory diseases of unknown etiology. "On the other hand, in a study on children with inflammatory bowel disease, RBP4 had a negative correlation with disease activity, which is conducive to the intervention of inflammation in disease development." (PMID 33505217, 2021).
intestinal tumors (1 paper, 2024). "In addition to serving as a carrier for retinol, STRA6 also acts as a cell surface signaling receptor for RBP4, influencing the occurrence of intestinal tumors and insulin secretion in pancreatic beta cells." (PMID 39518840, 2024).
left ventricular hypertrophy (1 paper, 2022). Enlargement of the LEFT VENTRICLE of the heart. "RBP4 may be related to the left ventricular hypertrophy, and carotid intra-medial membrane thickness (IMT), suggesting that RBP4 may serve as a marker of vascular injury in hypertensive patients at early stage." (PMID 35309061, 2022).